DNMT3B (DNA methyltransferase 3 beta)
Diseases named in the same sentence as DNMT3B in open-access papers (continued):
Sharing a sentence is not in itself a finding about the gene and the disease.
ICF syndrome (continued). "Three other genes are currently known to cause ICF syndrome upon mutation, among them DNA methyltransferase 3B (DNMT3B) (ICF1), mutations in zinc finger and BTB domain containing 24 (ZBTB24) (ICF2), and cell division cycle associated 7 gene (CDCA7) (ICF3)." (PMID 32727902, 2020). "Pathogenic variants in four genes have been shown to cause ICF syndrome: DNMT3B (ICF1), ZBTB24 (ICF2), CDCA7 (ICF3), and HELLS (ICF4)." (PMID 31066130, 2019). "Comparatively, a single mutation in the PWWP domain of DNMT3B was discovered in patients with ICF syndrome." (PMID 31091831, 2019). "Among all DNMTs, the disease-causing mutations were first discovered in DNMT3B in patients with immunodeficiency, centromeric instability, and facial anomalies (ICF) syndrome." (PMID 31091831, 2019). "In humans, biallelic loss of function mutations in DNMT3B lead to ICF syndrome which displays a wide range of phenotypes arising as a consequence of genome-wide methylation perturbations." (PMID 31738163, 2019). "For example, de novo mutation of the DNA methyltransferase DNMT3B leads to immunodeficiency-centromeric instability-facial anomalies syndrome (ICF syndrome)." (PMID 31440232, 2019). "In humans, DNMT3B mutations lead to the ICF syndrome (Immunodeficiency Centromeric instability Facial anomalies)." (PMID 29843609, 2018). "ICF syndrome is a rare genetic disorder caused by mutations in one of four identified genes: DNMT3b, HELLS, CDCA7, and ZBTB24." (PMID 30544645, 2018). "Mice harboring ICF-like mutations in Dnmt3b exhibit some characteristics of ICF syndrome including small size and facial anomalies." (PMID 30484769, 2018). "Most cases of ICF syndrome (55%) are caused by mutation in DNMT3b, the gene coding for the human de novo DNA methyltransferase." (PMID 30544645, 2018). "Here, we report the case of a 1-year-old boy of Moroccan consanguineous parents, who was diagnosed at 4 months of age with ICF syndrome with a homozygous missense mutation in the DNMT3B gene." (PMID 28713390, 2017). "Intriguingly, a mutation affecting the corresponding region in DNMT3B is observed in patients suffering from immunodeficiency, centromeric instability and facial anomalies (ICF) syndrome, an autosomal recessive disease caused by mutations in DNMT3B." (PMID 28854222, 2017). "One prominent example is the rare autosomal recessive Immunodeficiency, Centromeric Instability, Facial Anomalies (ICF) syndrome which, in about 60% of cases, is caused by mutations in the gene encoding the de novo DNA methyltransferase DNMT3B." (PMID 26974671, 2016). "Dysfunction in TERRA expression is linked to diseases, like the immunodeficiency, centromere instability, and facial anomalies (ICF) syndrome, a rare autosomal recessive immune disorder caused by mutations in the DNA methyltransferase gene DNMT3b." (PMID 25926849, 2015). "The ICF syndrome is caused by genetic defects in the catalytic activity of DNMT3B protein leading to genomic DNA hypomethylation and heterochromatin defects." (PMID 24616662, 2014). "Germ line gene mutations in DNMT3B are responsible for the autosomal recessive disease named Immunodeficiency with Centromeric instability and Facial anomalies (ICF syndrome)." (PMID 25198254, 2014). "DNMT3b mutant mice, humans with ICF Syndrome, and mice with ICF-like mutations exhibit craniofacial and cardiac defects." (PMID 23094090, 2012). "DNMT3b−/− mice die before craniofacial structures form, however, mice with missense mutations equivalent to those in patients with ICF syndrome exhibit delayed skull vault ossification, and shorter, wider frontal bones." (PMID 23094090, 2012). "Genetic deficiency of DNMT3B causes ICF syndrome, a recessive human disorder characterised by immunodeficiency, centromere instability, and facial anomalies." (PMID 21347319, 2011).
ICF syndrome (continued). "ICF syndrome was initially linked to chromosome 20q11.2 and subsequently the DNA methyltransferase 3B gene (DNMT3B) was identified as the gene responsible for the methylation defects observed in ICF." (PMID 20613881, 2010). "In this study, we systematically assessed the impact of these ICF syndrome‐associated mutations in the RD interface on the assembly, as well as enzymatic and DNA‐binding activities, of the DNMT3B‐3L complex, together with their impacts on structural folding and methylation sequence preferences." (PMID 39290110, 2024). "Pathogenic variants in four genes have been identified to cause ICF syndrome: DNA methyltransferase 3B gene (DNMT3B; ICF1), Zinc-finger and BTB domain-containing 24 gene (ZBTB24; ICF2), cell division cycle associated 7 gene (CDCA7; ICF3) and helicase lymphoid specific gene (HELLS; ICF4)." (PMID 39167297, 2024). "Recessive mutations in CDCA7 or DNMT3B can cause ICF syndrome." (PMID 38335290, 2024). "In conclusion, our study furnishes compelling biophysical, biochemical, and structural evidence of the molecular mechanisms underlying how mutations in the RD interface of the DNMT3B homodimer may contribute to the onset of ICF syndrome." (PMID 39290110, 2024). "ICF syndrome has been linked to defects in four genes, namely DNMT3B, ZBTB24, CDCA7, and HELLS." (PMID 39290110, 2024). "The first mutations in a DNMT gene that were associated with a disease were mutations in DNMT3B, found in patients with immunodeficiency, centromere instability, and facial abnormalities (ICF) syndrome, which is named after the characteristic abnormalities observed during its development." (PMID 39334883, 2024). "This may be relevant to ICF syndrome patients with HELLS mutations, given that hypomethylation of repeat sequences is observed at a subset of chromosomes and the most frequently observed mutations in ICF syndrome are within DNMT3b." (PMID 31802118, 2020). "Here, we report the case of a 1-year-old boy of Moroccan consanguineous descent diagnosed with ICF syndrome carrying a homozygous missense mutation in the DNMT3B gene (Ala603Thr) with hypogammagobulinemia, normal B cell count, facial anomaly, and failure to thrive." (PMID 28713390, 2017). "Our findings also shed new light on the possible molecular dysfunctions caused by the mutations of DNMT3B in the human ICF syndrome and might help to identify new epigenetically deregulated targets for diagnosis." (PMID 25476147, 2014). "A primary role for Dnmt3b in Xi CGI methylation is consistent with a previous study that showed reduced Xi CGI methylation in lymphoblastoid cell lines from females with immunodeficiency-centromeric instability-facial anomalies (ICF) syndrome, which is caused by mutations in the human DNMT3B gene." (PMID 22841499, 2012). "Likewise, humans with DNMT3b mutations exhibit the rare autosomal recessive disorder Immunodeficiency, Centromeric instability and Facial anomalies (ICF) Syndrome and have craniofacial defects such as hypotelorism, a shorter nose and a wider nasal bridge." (PMID 23094090, 2012). "Most recently, a model for ICF syndrome has been engineered by generating Dnmt3b mutations in mice." (PMID 20613881, 2010). "ICF syndrome (standing for Immunodeficiency, Centromere instability and Facial anomalies syndrome) is a very rare autosomal recessive immune disorder caused by mutations of the gene de novo DNA-methyltransferase 3B (DNMT3B)." (PMID 20211012, 2010). "Altogether, our study uncovers a wide array of fundamental defects triggered by DNMT3B mutations, including the disassembly of DNMT3B dimers, reduced DNA‐binding capacity, and alterations in flanking sequence preferences, leading to aberrant DNA hypomethylation and ICF syndrome." (PMID 39290110, 2024).
ICF syndrome (continued). "This latter hypothesis is based on analyses of hypomethylated cells obtained either from cells treated with DNA-methyltransferase inhibitors (5-azacytidine) or from cells from patients with ICF syndrome who have mutations in the DNA methyltransferase 3b gene (DNMT3B)." (PMID 29636833, 2018). "In summary, mutations in DNMT3b, ZBTB24, CDCA7, and HELLS disturb the normal process of DNA methylation, which is critical to the pathogenesis of ICF syndrome." (PMID 39376563, 2024). "In a study on patients with ICF syndrome, Hansen and coworkers found three SNPs located in different regions of the DNMT3B gene, two of which create substitutions V726G and A603T, and one SNP that is located in an intronic part of the gene." (PMID 39334883, 2024). "Taken together, this study establishes an etiological role of DNMT3B oligomerization in ICF syndrome." (PMID 35869095, 2022). "ICF syndrome patients can be classified based on the impaired gene, in addition to DNMT3B (ICF1): ZBTB24 (zinc-finger and BTB domain-containing 24, ICF2), CDCA7 (cell division cycle-associated 7, ICF3), and HELLS (helicase, lymphoid-specific, ICF4)." (PMID 31963661, 2020). "Note that two of these mutations, N658S and R823P, are associated with ICF syndrome, which reinforces the etiologic link between DNMT3B and the ICF syndrome." (PMID 32620778, 2020). "ICF1 is caused by mutations in DNMT3B, which is responsible for the hypomethylation of satellites II and III, which is considered the hallmark of ICF syndrome." (PMID 32481609, 2020). "ICF1 is caused by biallelic mutations in DNMT3B, which encodes the DNA methyltransferase 3B and is the most frequent type of ICF syndrome, accounting for approximately half of patients." (PMID 30987377, 2019). "This is the case of ICF syndrome, the extremely rare genetic syndrome that is a fundamental source of the molecular findings about DNMT3B function." (PMID 30406101, 2018). "The ectopic expression of these genes is a common feature in ICF syndrome and cancer cells showing DNMT3B dysfunction." (PMID 30406101, 2018). "Direct or indirect loss of DNMT3B activity consequently decreased satellite DNA methylation in ICF syndrome patients, indicating that DNMT3B is involved in maintaining genome stability." (PMID 27446199, 2016). "In conclusion, this study contributes in clarifying the direct relationship between DNA methylation defect and gene expression impairment in ICF syndrome, identifying novel direct target genes of DNMT3B." (PMID 26161907, 2015). "It is of great interest that a S282P mutation in the DNA methyltransferase 3b (DNMT3b, also a PWWP protein) gene results in the ICF syndrome (for immunodeficiency, centromeric instability, and facial anomalies)." (PMID 21489262, 2011). "More generally, we suggest that DNMT3B plays a role in DNA methylation homeostasis at heterochromatin, a process which is disrupted in cancer, aging and Immunodeficiency, Centromeric Instability and Facial Anomalies (ICF) syndrome." (PMID 38291337, 2024). "However, as the knock-out of Dnmt3b in mice produces prenatal death, ICF syndrome patients probably conserve some residual activity of DNMT3b, concordantly with in vitro assays and mouse models of ICF mutations." (PMID 31963661, 2020). "Thus, addressing the reversibility of DNMT3B and LSH deficiency-caused phenotypes in differentiated cells is instrumental to motivate further research into improved therapies for ICF syndrome patients." (PMID 27179028, 2016). "It seems accepted that is the DNA methylation deficiency, and not other aspects of impaired DNMT3b activity, responsible for the ICF syndrome." (PMID 26161907, 2015). "Accordingly, we asked whether de novo methylation of DNMT3B-target repetitive genomic regions also occurs in human ICF syndrome fibroblasts." (PMID 23450006, 2013).
ICF syndrome (continued). "Mentioned phenotypic and cytogenetic characteristics alluded to the rare ICF syndrome, however, both of siblings had not detectable mutation in the DNMT3B gene but only the identical polymorphisms were found." (PMID 20211012, 2010). "These exceptions further implicateloss of DNA methylation, and not some other biological activity of DNMT3B, as the upstream molecular defect causing the ICF syndrome." (PMID 18432406, 2008). "Furthermore, the DNMT3B DNA methyltransferase gene mutated in the ICF immunodeficiency syndrome was sequenced in P1 and P2 and no hint on a mutation was detected, thus, excluding a common ICF syndrome." (PMID 20211012, 2010). "For example, studies of Dnmt3b null and ICF mutant mice have shown that Dnmt3b is essential for mouse embryonic development and that the ICF mice exhibit phenotypes that resemble some of the symptoms of the human ICF syndrome." (PMID 29636833, 2018). "In addition, it is unknown whether ectopic expression of DNMT3B in non-embryonic cells of ICF syndrome patients, may restore normal methylation patterns at subtelomeric regions." (PMID 23450006, 2013).
colorectal cancer (61 papers, 2007 to 2025). A primary or metastatic malignant neoplasm that affects the colon or rectum. "In a previous meta-analysis based on 24 case-control studies, the DNMT3b rs1569686 G allele has been identified as a low risk factor for developing colorectal cancer." (PMID 26262893, 2015). "Over-expression of DNMT3B promotes tumorigenesis in a mouse model of colorectal cancer and is associated with the hypermethylation of specific genes." (PMID 23034185, 2012). "The aim of this study was to examine the association between the -149C>T polymorphism of DNA methyltransferase 3B (DNMT3B) and colorectal cancer (CRC) susceptibility." (PMID 23170134, 2012). "Carriers with the G allele in the DNMT3B gene were found to have a decreased risk of colorectal cancer compared with individuals with the T allele." (PMID 18662374, 2008). "In the current study, we investigated the influence of DNMT3B polymorphisms -149 C>T and -579G > T on the risk of colorectal cancer in a hospital-based case-control study in a Chinese population." (PMID 18662374, 2008). "Since genetic polymorphisms often vary between ethnic groups, further studies are needed to clarify the association of the DNMT3B polymorphism with colorectal cancer in diverse ethnic populations." (PMID 18662374, 2008). "The association between two SNPs of the DNMT3B promoter and the risk of the development of colorectal cancer was analyzed in a population of Chinese." (PMID 18662374, 2008). "Moreover, in the subgroup analysis, DNMT3B -579G/T appeared to contribute to decreased risk of lung and colorectal cancer, whereas DNMT3B -149C/T was associated with a decreased risk of head and neck cancer." (PMID 33369477, 2020). "Moreover, it has recently been shown that DNMT3B overexpression is closely associated with the emergence of the CIMP phenotype in colorectal cancer." (PMID 22563479, 2012). "In addition, DNMT3B overexpression is associated with CIMP-high phenotype in colorectal cancer." (PMID 28090275, 2017). "However, and surprisingly given our findings, recent work in mouse ESCs, derived neuronal progenitors, and the human colorectal carcinoma HCT116 cell line have showed that it is principally DNMT3B (and to a lesser extent DNMT3A) that is associated with gene-body methylation." (PMID 26408185, 2015). "The DNMT3b -579G>T polymorphism may contribute to the genetic susceptibility to colorectal cancer." (PMID 18662374, 2008). "However, the DNMT3B -579G>T polymorphism may contribute to the genetic susceptibility to colorectal cancer." (PMID 18662374, 2008). "In contrast, increased DNMT3B expression has been reported in colorectal cancer, while the deletion of Dnmt3a inhibits colorectal cancer development." (PMID 39819598, 2025). "In another study, methyltransferase DNMT3B was identified as a factor that stimulates the proliferation of colorectal cancer cells." (PMID 40531759, 2025). "DNMT3B-positive staining is challenging to detect in normal tissues but readily observable in colorectal cancer tissues." (PMID 39108206, 2024). "The clinical relevance of DNMT3B in colorectal cancer has been a focus of research, with efforts directed towards assessing its potential as a diagnostic biomarker or therapeutic target." (PMID 39108206, 2024). "The rate of high DNMT3B expression in colorectal cancer tissue was 80%, which was significantly greater than that in normal tissue." (PMID 39108206, 2024). "DNMT3B controls colorectal cancer cell proliferation through PLCG2, which is useful for developing therapeutic approaches that target PLCG2 expression for the treatment of colorectal cancer." (PMID 39108206, 2024). "To validate the expression level of DNMT3B in clinical tumor tissues, we collected clinical tissue samples from 80 patients with a history of colorectal cancer surgery at Northern Jiangsu People’s Hospital." (PMID 39108206, 2024).